JAK2 (Janus kinase 2)
Diseases named in the same sentence as JAK2 in open-access papers (continued):
Sharing a sentence is not in itself a finding about the gene and the disease.
hepatocellular carcinoma (110 papers, 2011 to 2026). A malignant tumor that arises from hepatocytes. "Activation of JAK2/STAT3 signaling is associated with enhanced radioresistance of hepatocellular carcinoma cells." (PMID 30551687, 2018). "This study aimed to detect the role of JAK2 rs V617F mutation in patients with chronic liver disease (cirrhosis and hepatocellular carcinoma) and clarify its value as a new risk factor for the development of portal vein thrombosis compared to other conventional thrombophilic factors." (PMID 33507708, 2021). "Subsequent examinations of BSCA-activated hepatocellular carcinoma cells revealed alterations in the gene expression of JAK2 and STAT3, as well as changes in the levels of p-JAK2 and p-STAT3 proteins." (PMID 39940837, 2025). "In conclusion, our study suggests that BSCAs can induce apoptosis in hepatocellular carcinoma cells and modulate the JAK2/STAT3 signaling pathway in hepatocellular carcinoma cells." (PMID 39940837, 2025). "In hepatocellular carcinoma (HCC) B7-H3 promotes cell invasion by targeting epithelial-mesenchymal transition (EMT) via partially activating JAK2/STAT3/Slug signaling pathway." (PMID 39664380, 2024). "Secondly, more comprehensive in vivo and in vitro studies are necessary to elucidate the mechanisms of TUG1 promotes hepatocellular carcinoma immune evasion via upregulating the JAK2/STAT3/PD-L1 signaling pathway." (PMID 37813900, 2023). "In the present study, it was demonstrated that notopterol suppresses hepatocellular carcinoma cell viability by inhibiting JAK2 activation and enhancing oxidative stress." (PMID 37299411, 2023). "Exons 1 and 4 of SOD2 transcripts were back-spliced to develop circSOD2, inducing epigenetic alteration and driving hepatocellular carcinoma progression by activating the JAK2/STAT3 signaling pathway." (PMID 38139387, 2023). "Meanwhile, suppressed proliferation in hepatocellular carcinoma cells or the inhibition of glycolysis was achieved by the blocking of the JAK2/STAT3 pathway." (PMID 36431990, 2022). "Carboxypeptidase X M14 family member 2 overexpression promotes proliferation and migration, predicts an unfavorable prognosis of osteosarcoma, and accelerates progression through the regulation of the gp130/JAK2/Stat1 pathway in hepatocellular carcinoma." (PMID 35686102, 2022). "For example, MUC1 was shown to promote radioresistance in hepatocellular carcinoma cells through activation of JAK2/STAT3 signaling." (PMID 35410995, 2022). "PRPF3 was reported to be a potential prognostic indicator in hepatocellular carcinoma and promoted the cell growth, migration, and invasion of keratinocyte-derived cutaneous squamous cell carcinoma via the JAK2/STAT3 pathway." (PMID 35260078, 2022). "Previous studies reported that Icaritin inhibits the growth of liver cancer cells through promoting the apoptosis of hepatoma cells by activating the caspase pathway and inhibiting the IL-6/Jak2/Stat3 signaling pathway." (PMID 33794968, 2021). "JAK2 RS V617F mutation was found in 28/100 (28%) in idiopathic PVT complicating liver cirrhosis and hepatocellular carcinoma." (PMID 33507708, 2021). "Quercetin inhibited hepatocellular carcinoma progression by modulating cell apoptosis, migration, invasion, and autophagy; and its effects were at least partly related with the JAK2/STAT3 signaling pathway." (PMID 31273958, 2019). "CT inhibited the proliferation of mouse hepatoma (Hepa1-6) cells in vitro by inducing Hepa1-6 cells apoptosis through the JAK2/STAT3 signaling pathway." (PMID 31161238, 2019). "Aberrant methylation of SOCS1 silences SOCS1 and activates the JAK2/STAT3 pathway in hepatocellular carcinoma cells (HCC), resulting in the development of HCC." (PMID 30285793, 2018). "Recent work has shown that B7-H3 promotes the aggression and invasion of hepatocellular carcinoma by targeting EMT transition via the JAK2/STAT3/Slug signaling pathway." (PMID 29190910, 2017).
hepatocellular carcinoma (continued). "It haspreviously been reported that prolonged (8–24 h) but not short-term(4 h) insulin pretreatment inhibits GH signaling via the GHR/JAK2/STAT5Bpathway in rat hepatoma cells." (PMID 21559284, 2011). "This interaction leads to a significant reduction in the phosphorylation of downstream signaling pathways, including focal adhesion kinase (FAK) and janus kinase 2 (JAK2), which was the main target market for acacetin in the human hepatocellular carcinoma cell line, HepG2." (PMID 39860214, 2025). "Molecular docking simulations of various BSCA components with JAK2 and STAT3 proteins indicated specific components with higher binding affinities, suggesting their potential to induce apoptosis in hepatocellular carcinoma cells by modulating the JAK2/STAT3 pathway." (PMID 39940837, 2025). "Adaptor C21orf58 formed a ternary complex with signal transducer and activator of transcription 3 (STAT3) and Janus kinase 2 (JAK2) to activate wild‐type and constitutively mutated STAT3, enhancing the capacities of malignant growth and sorafenib resistance to hepatocellular carcinoma (HCC) cells." (PMID 38342622, 2024). "Furthermore, B7-H3 promotes EMT in glioma and hepatoma cells through JAK2/STAT3/Slug pathway activation." (PMID 38468228, 2024). "Quercetin could exert antitumor effects by preventing hepatocellular carcinoma LM3 cells from proliferating, migrating and invading, causing cell cycle arrest and apoptosis and stimulating HCC autophagy via abrogating the JAK2/STAT3 signaling pathway (by downregulating JAK2 and STAT3)." (PMID 36837850, 2023). "Similarly, Quercetin inhibits hepatocellular carcinoma progression by down-regulation of the activation of JAK2 and STAT3." (PMID 36195876, 2022). "MiR-337-3p functioned as a tumor suppressor in hepatocellular carcinoma cells by targeting JAK2." (PMID 30939162, 2019). "JAK2 was shown to mediate autophagy in hepatoma and U87 glioblastoma cells." (PMID 28094778, 2017). "Of importance, we found that Jak2 was a key interactant of Gab2 in hepatoma cells." (PMID 28842424, 2017). "Icaritin, a bioactive compound sourced from desiccated epimedium stems and leaves, dampens glycolytic processes mediated by GLUT1 in hepatocellular carcinoma (HCC) cells through the impediment of Janus kinase 2 (JAK2)/STAT3 pathway activation." (PMID 40417000, 2025). "In light of the pivotal role of inflammation in driving hepatocellular carcinoma progression, we next sought to determine whether the anti‐cancer effect of FPHPE involves modulation of the JAK2/STAT3 pathway—a central mediator of tumor‐associated inflammation and survival." (PMID 41200213, 2025). "In in vitro experiments with co-cultured TAMs and hepatocellular carcinoma cells it was shown that M2-like cells produce IL-8 which upregulates EMT markers in HCC cells via the JAK2/STAT3 pathway." (PMID 38794298, 2024). "In addition, NLRC3 silencing may play an important role in cancer progression and prognosis of hepatocellular carcinoma via the activation of Janus kinase 2/signal transducers and the transcription 3 (JAK2/STAT3) pathway under interleukin-6 (IL-6) stimulation." (PMID 37964222, 2023). "Moreover, WT1-AS could upregulate expression of WT1 to inhibit hepatocellular carcinoma cell proliferation and apoptosis via activating JAK2/STAT3 and MAPK signaling pathway." (PMID 30406146, 2018). "Studies confirm its regulatory influence over hepatocellular carcinoma progression through SIRT1 modulation and its intimate link with hepatoblastoma via angiogenic control mediated by the JAK2/STAT3 pathway." (PMID 41523988, 2026). "Previous studies have demonstrated that ZZXJD induces autophagy and apoptosis in hepatocellular carcinoma cells via the AKT/mTOR and JAK2/STAT3 signaling pathways, resulting in programmed cell death and inhibition of HCC progression." (PMID 40303917, 2025).
hepatocellular carcinoma (continued). "To validate these findings, we conducted a Western blot analysis to examine the levels of p-JAK2/t-JAK2 and p-STAT3/t-STAT3 proteins—pivotal components of the signaling pathway—in hepatocellular carcinoma cells." (PMID 39940837, 2025). "In hepatocellular carcinoma (HCC) cells, MUC1 can promote radio resistance by activating the JAK2/STAT3 signaling pathway." (PMID 38164273, 2024). "In the progression of non-alcoholic steatohepatitis (NASH), NASH-related hepatocellular carcinoma (HCC), and liver cancer, NIK and JAK2/STAT5 signaling in the liver play a significant role." (PMID 38577603, 2024). "By investigating the impact of vitexin on the STAT3 signaling pathway and key cancer markers, researchers have demonstrated that vitexin can successfully disrupt the sustained activation of JAK1, JAK2, and STAT3 in hepatocellular carcinoma (HCC) cells." (PMID 38915462, 2024). "In Hepatocellular Carcinoma (HCC), circ_0072088 activates JAK2/STAT3 signaling pathway and enhances the proliferation, migration, and invasion ability of HCC cells." (PMID 38006726, 2023). "Besides, in bufothionine-treated SMMC-7721 hepatocellular carcinoma cells, it could be observed that the concentration of IL-6 was decreased, the expression of p-Stat3-tyr705, p-Stat3ser727, and JAK2 was downregulated, as well as there was an increase in Atg5, Atg7, and LC3-II." (PMID 36104717, 2022). "Inhibition of the JAK2/STAT3 pathway induced by ANGPTL1 represses angiogenesis and metastasis in hepatocellular carcinoma." (PMID 35980290, 2022). "This study suggests that STAT1 may be a key oncogene in hepatocellular carcinoma and provides evidence that the JAK2 inhibitor lestaurtinib is a potent antiproliferative agent that warrants further investigation as a targeted therapy for HCC." (PMID 35646925, 2022). "Bicuculline can effectively inhibit the migration and invasion of human hepatocellular carcinoma MHCC97-H cells which is related to the downregulation of VEGF, MMP-2, and MMP-9 gene expression and inhibition of JAK2/STAT3 signaling pathway activation." (PMID 34497656, 2021). "Given that IL-6 plays a key role in regulating inflammatory hepcidin expression by activating STAT3, we examined the roles of DP in the expression of JAK2, p-JAK2, STAT3, and p-STAT3 in HepG2 hepatoma cells treated with IL-6." (PMID 33488942, 2021). "The JAK2/STAT3 pathway is activated downstream B7-H3-induced signaling which is in agreement with reports of the B7-H3 role in multiple myeloma, hepatocellular carcinoma, and glioma cell lines." (PMID 33426073, 2020). "In summary, our study demonstrated the preclinical activity of PH, which inhibits hepatic carcinoma in vitro and in vivo and prolonged mouse survival via molecular targeting of STAT3/Akt/mTOR/JAK2/VEGF2 pathways." (PMID 31619257, 2019). "At the post-receptor level, prolonged treatment with insulin is known to inhibit JAK2/STATs signaling by reducing JAK2 and STAT5 phosphorylation and protein content of STAT3, e.g., in H4IIE hepatoma cells." (PMID 29977227, 2018). "A separate analysis of the mutually independent roles of JAK2 and SRC in downstream signaling activation and cell fate, similar to studies done in pre-adipocytes and human hepatoma cells, would be of interest and value to resolve in further studies." (PMID 28223541, 2017). "AG490 (Jak2 inhibitor), or bafilomycin A1 (autophagic flux inhibitor) both inhibited the IFN-γ-triggered LDH release in Con A-treated hepatoma cells." (PMID 22163006, 2011). "Moreover, PTPRO dephosphorylated JAK2 and downregulated JAK2/STAT3 signaling in hepatocellular carcinoma." (PMID 38182570, 2024). "Also, in hepatocellular carcinoma, lncRNA DLGAP1 antisense RNA 1 (DLGAP1-AS1) activates Janus kinase 2 (JAK2)/STAT3 signaling pathway by sponging miR-26a-5p and miR-26b-5p." (PMID 36737782, 2023).
hepatocellular carcinoma (continued). "In vitro studies demonstrated that AZD1480, an ATP-competitive inhibitor of JAK1 (Janus kinase 1) and JAK2 (Janus kinase 2), could inhibit HAV genotype III replication in human hepatoma cells." (PMID 37243166, 2023). "DLGAP1-AS1 sequestered miR-486-5p to promote cell proliferation of hepatocellular cancer, and DLGAP1-AS1 urged the occurrence of liver cancer and epithelial-mesenchymal transition through the feedback loop of the miR-26a/b-5p/IL-6/JAK2/STAT3 and Wnt/β-catenin pathways." (PMID 35341001, 2022). "Increasing evidence demonstrates JAKs as a prognostic biomarker and therapeutic target for many cancers or other diseases, such as JAK3 for renal cell carcinoma, JAK2 for acute lymphoblastic leukemia, JAK2 for skin cutaneous melanoma, and TYK2 for hepatocellular carcinoma." (PMID 33083484, 2020). "Moreover, JAK2 and TYK2 were suggested to be potential biomarkers for the diagnosis of hepatocellular carcinoma." (PMID 33083484, 2020). "ROS-mediated JAK2 inhibition by GSH depletion could inhibit cell growth and induce apoptosis in hepatocellular carcinoma cells." (PMID 31438997, 2019). "In addition, the Jak2 inhibitor, AG490, markedly restrained the ability of Gab2 to promote hepatoma cell proliferation and metastasis." (PMID 28842424, 2017). "Moreover, inhibition of constitutive STAT3 signaling by the JAK2 inhibitor AG490 suppressed the growth and invasion of human hepatocellular carcinoma cells, and also induced apoptosis in multiple myeloma cells." (PMID 26417930, 2015). "In addition to JAK-1, IL-6/JAK-2/STAT3 activation and tumor progression in hepatocellular carcinoma has recently been reported." (PMID 23555719, 2013). "For 3T3-F442A preadipocytes and H4IIE hepatoma cells it has been shown that relative levels of JAK2 and SRC family kinase in any particular cell might determine which kinase is the major signaling element, with JAK2 predominating in most cases." (PMID 33312162, 2020). "Consistently in experiments performed in vitro, B7-H3 was able to stimulate the wound healing, metastasis and invasion of hepatoma cells by targeting epithelial-to-mesenchymal transition (EMT) via JAK2/Stat3/Slug signaling pathway, while no obvious influence on cell growth and apoptosis." (PMID 25908926, 2015). "This idea is supported by the report in H4IIE hepatoma, in which insulin co-treatment can enhance GH-induced MEK1/2 and ERK1/2 phosphorylation independent of JAK2/STAT5 activation." (PMID 29977227, 2018). "Similarly, in hepatocellular carcinoma (HCC), toosendanin (TSN), a novel agonist of WWOX, dose-dependently increases WWOX mRNA and protein expression and enhances its interaction with STAT3 and Dvl2, thereby inhibiting both the JAK2/STAT3 and Wnt/β-catenin signaling pathways." (PMID 41228229, 2025).
Thrombocytosis (109 papers, 2006 to 2026). Increased numbers of platelets in the peripheral blood. "By contrast, pegylated interferon-α (Peg-IFNα) has shown efficacy in controlling thrombocytosis, reducing spleen size, and improving symptom burden, with notable molecular responses, particularly in JAK2 V617F–mutated cases." (PMID 41228192, 2025). "Further studies will be needed to clarify the role of JAK2-R1063H (as well as the role of other germline mutations associated with thrombocytosis), in the regulation of both pathways." (PMID 40841769, 2025). "Based on positive screening for thrombocytosis and the Janus kinase 2 V617F mutation, he was diagnosed with ET." (PMID 40809165, 2025). "The V617F status of JAK2 is suggested to identify the RARS-T (refractory anemia with ringed sideroblasts associated with marked thrombocytosis) subtype of MDS, which was shown to correlate with better prognosis." (PMID 41462997, 2025). "JAK2 V617F mutations are also associated with a higher risk of thrombosis and leukemic transformation, particularly when combined with extreme thrombocytosis and/or abnormal karyotypes." (PMID 40507313, 2025). "Recognized risk factors include JAK2 mutations, chromosomal abnormalities, and extreme thrombocytosis (platelet count ≥1000 × 109/L)." (PMID 40376591, 2025). "were associated with JAK2, and mutations associated with thrombocytosis were identified, leaving room for potential drug relationships." (PMID 38302579, 2024). "Patient 11 had a family history of primary thrombocytosis, and Janus Kinase 2 V617F mutation (JAK2 V617F) was detected during follow-up." (PMID 38822265, 2024). "The SF3B1 mutation correlated strongly with ring sideroblasts in the bone marrow, and the presence of SF3B1/JAK2 mutations along with ring sideroblasts and thrombocytosis can be used to establish the diagnosis of MDS/MPN-RS-T." (PMID 39337700, 2024). "Although post-splenectomy reactive thrombocytosis was evident, it was tempting to raise the possibility of ET based on the JAK2 mutation, bone marrow biopsy, and the long-lasting thrombocytosis during the following 6 years." (PMID 36923225, 2023). "Clinically, patients with PV harboring the JAK2V617F mutation exhibit pancytosis, including leukocytosis, thrombocytosis, and erythrocytosis, whereas those harboring the JAK2 exon 12 mutation show only an aggressive increase in red cell mass." (PMID 37629188, 2023). "Individuals with thrombocytosis, compared with their matched controls, had a higher prevalence of JAK2 (12.8% vs 1.1%; P < 0.001) (all V617F mutations) and CALR mutations (4.7% vs 0.0%; P = 0.003)." (PMID 36698617, 2023). "The combination of thrombocytosis and JAK2/MPL/CALR mutations is highly suggestive for undiagnosed MPN or a premalignant condition, while other gene mutations seem to have no relevance in these cases." (PMID 36698617, 2023). "In this entity, it was found that the SF3B1 mutation drives the formation of ring sideroblasts and that the JAK2 V617F mutation drives the thrombocytosis." (PMID 36810551, 2023). "In total, 11 of 14 individuals with thrombocytosis that carried a JAK2 mutation at baseline with available follow-up data had persistent thrombocytosis (78.6%)." (PMID 36698617, 2023). "For example, it is known now in MDS/MPN with ring sideroblasts and thrombocytosis (MDS/MPN-RS-T) that the JAK2 V617F mutation drives the thrombocytosis while the SF3B1 mutation drives the increased ring sideroblasts." (PMID 36810551, 2023). "This indicates that the SF3B1 mutation triggers pancytopenia in the cells and then the JAK2 mutation is acquired as a second-hit mutation, causing thrombocytosis in the patient to rescue the pancytopenia to some extent." (PMID 37629188, 2023). "One patient (Pt2), with thrombocytosis and JAK2 variant, is currently treated with low dose acetylsalicylic acid (ASA)." (PMID 36419910, 2022). "Pathogenic JAK2 variants can cause hereditary thrombocytosis and hereditary erythrocytosis with autosomal dominant inheritance." (PMID 34946900, 2021).